CYP11A1 (cytochrome P450 family 11 subfamily A member 1)
Diseases named in the same sentence as CYP11A1 in open-access papers (continued):
Sharing a sentence is not in itself a finding about the gene and the disease.
adrenal hypoplasia (3 papers, 2007 to 2016). "For example, FGD/FGD-like conditions (MC2R, MRAP, NNT gene defects) can present with salt loss suggestive of adrenal hypoplasia, and alterations in STAR and CYP11A1 resulting in partial loss of protein function may have a predominant FGD-like phenotype (17, –, 20)." (PMID 26523528, 2016).
Allergy (3 papers, 2020 to 2023). An allergy is an immune response or reaction to substances that are usually not harmful. "The genes HPGDS and CYP11A1 were part of both lipid metabolism and allergy subsets, in line with their function in prostaglandin metabolism." (PMID 36725846, 2023). "Previous studies have shown that the steroidogenic enzyme Cyp11a1 can affect the secretion function of CD8+ T lymphocyte suppressor by regulating lipid metabolism and promoting allergic reactions." (PMID 37511510, 2023). "In the current study, in children with evidence of sensitization to peanut (positive skin prick test) and/or peanut-specific IgE) and allergy confirmed in many on DBPCOFC, we determined if expression of CYP11A1 was increased in peripheral blood CD4+ T cells from PA children." (PMID 32497050, 2020).
colitis (3 papers, 2019 to 2023). Inflammation of the colon. "In line with the increased activity of LRH‐1 in SHP‐deficient mice, we observed increased colitis‐induced expression of the steroidogenic enzymes Cyp11a1 and Cyp11b1, and associated production of colonic corticosterone." (PMID 36861295, 2023). "In a dextran sodium sulfate-induced mouse colitis model, intestinal GC synthesis and the expression levels of cytochrome P450 family 11 subfamily A member 1 (Cyp11a1) and subfamily B member 1 (Cyp11b1) were rapidly upregulated." (PMID 36362361, 2022). "Additionally, in a murine model of colitis we confirmed that colitis-induced expression of the steroidogenic enzymes Cyp11a1, Cyp11b1, and Cyp21 is LRH-1-dependent since their induction was significantly reduced in LRH-1 intestine-specific knockout mice." (PMID 31316505, 2019).
Follicular Cyst (3 papers, 2022 to 2023). Cyst due to the occlusion of the duct of a follicle or small gland. "Here, during the formation of porcine follicular cysts, excess cortisol might have affected the mRNA expressions of StAR, CYP11A1, and 3β-HSD, resulting in abnormally elevated levels of progesterone in FF." (PMID 35158681, 2022). "The Kyoto Encyclopedia of Genes and Genomes (KEGG) analysis linked the ovarian steroidogenesis pathway, especially the STAR, 3β-HSD, CYP11A1 and CYP17A1 genes, to the formation of follicular cysts (p < 0.01)." (PMID 37958056, 2023). "In this study, through transcriptomic analysis of TIMG cells, we found that StAR and CYP11A1, as well as CYP17A1 and 3β-HSD were significantly enriched in the signaling pathway of cortisol synthesis and secretion in follicular cysts." (PMID 38274662, 2023).
glioma (3 papers, 2020 to 2024). A benign or malignant brain and spinal cord tumor that arises from glial cells (astrocytes, oligodendrocytes, ependymal cells). "In our study, we showed that StAR and CYP11A1 did not display any significant circadian variations in glioma cells, whereas TSPO levels followed a circadian rhythm in vitro and in vivo (mouse brain lysates)." (PMID 33086741, 2020).
leukemia (3 papers, 2010 to 2024). A malignant (clonal) hematologic disorder, involving hematopoietic stem cells and characterized by the presence of primitive or atypical myeloid or lymphoid cells in the bone marrow and the blood. "We first analysed the DA1-3b leukemia model and among the 70 commonly mutated genes in dormant leukemia DA1-3b/D365 and parental DA1-3b cells, ten genes (Ttc7b, Dnmt3b, Ap1b1, Ne1, Nedd4, Acy1, Cyp11a1, Htr2c, Magee1 and Gdi1) were amplified in dormant and parental cells." (PMID 39223638, 2024). "In addition, 20(OH)D3, a novel product of vitamin D3 metabolism by CYP11A1, has strong antiproliferative activity in keratinocytes and anticancer activity in leukaemia lines." (PMID 22095230, 2011).
lipoid adrenal hyperplasia (3 papers, 2015 to 2021). "CYP11A1 localizes to mitochondria and produces steroid hormones, and deficiency of these hormones causes congenital lipoid adrenal hyperplasia." (PMID 34752660, 2021). "In humans, mutation of CYP11A1 can cause congenital lipoid adrenal hyperplasia, with a range of symptoms such as male sex reversal, high plasma adrenocorticotropic hormone levels, and increased plasma concentrations of gonadotrophins." (PMID 26580217, 2015).
colon cancer (2 papers, 2022 to 2023). "In colon cancer, CYP11A1 appears to be frequently downregulated." (PMID 36861295, 2023).
cryptorchidism (2 papers, 2016 to 2021). The failure of one or both testes of a male fetus to descend from the abdomen into the scrotum during the late part of pregnancy. "One of the four boys with the p.R451W mutation in CYP11A1 had a small penis and cryptorchidism." (PMID 26523528, 2016).
diabetes (2 papers, 2010 to 2025). "As reported in prior studies, STZ-induced diabetes decreased Star expression, consistent with our findings, whereas Cyp11a1 and Hsd17b3 mRNA levels showed no significant changes." (PMID 41158715, 2025).
hyperglycaemia (2 papers, 2020 to 2022). "Chinese scientists reported that in Leydig cells under the conditions of severe hyperglycemia and increased levels of advanced glycation end products, expression of the Star, Cyp11a1 and Hsd3b genes was reduced." (PMID 33050653, 2020).
Hypoglycemia (2 papers, 2021 to 2024). A decreased concentration of glucose in the blood. "Partial loss of CYP11A1 or STAR can present in childhood with ketotic hypoglycemia." (PMID 34258490, 2021).
hypothyroidism (2 papers, 2023 to 2025). Abnormally low levels of thyroid hormone. "When we evaluated the expression of key enzymes in the steroidogenic cascade, hypothyroidism reduced testicular Star and Cyp11a1 expression." (PMID 37798396, 2023). "Regarding transporter protein and steroidogenic enzyme expression, hypothyroidism reduced Star (*P < 0.05) and Cyp11a1 (***P < 0.001) mRNA levels compared to control, and Kp10 did not revert these changes." (PMID 37798396, 2023). "While Kp10 treatment did not reestablish the change in Star and Cyp11a1 expression caused by hypothyroidism, it increased nuclear receptor subfamily 5 group A member 1 (Nr5a1), also named steroidogenic factor 1, which is an important transcription factor for testicular steroidogenesis." (PMID 37798396, 2023).
kidney cancer (2 papers, 2022 to 2023). Primary or metastatic malignant neoplasm involving the kidney. "Our findings suggest that CYP11A1 may act as a therapeutic target to suppress kidney cancer proliferation while causing negligible effects on normal cells." (PMID 36182900, 2022). "Here, we established a CYP11A1-overexpressing Caki-1 cell line as an efficient screening platform for the identification of active compounds against kidney cancer and used it to screen a panel of 1374 natural compounds." (PMID 38036976, 2023). "In this context, natural compounds that exhibit potent CYP11A1 stimulation activity can be promising therpaeutic agents for kidney cancer." (PMID 38036976, 2023). "This study indicates that the CYP11A1-overexpressing Caki-1 cell line is useful for screening drugs against kidney cancer." (PMID 38036976, 2023). "We recently reported that overexpression of CYP11A1 reverses the epithelial-mesenchymal transition by arresting the kidney cancer cells in G2/M phase." (PMID 38036976, 2023). "We previously found that overexpression of CYP11A1 inhibited epithelial-mesenchymal transition and induced G2/M arrest in the kidney cancer Caki-1 cell line." (PMID 38036976, 2023). "Together with the migration, invasion, and viability assay findings, these results confirm that CYP11A1 overexpression inhibits cancer cell proliferation in kidney cancer cells." (PMID 36182900, 2022). "In this regard, it is vital to highlight the molecular mechanisms of CYP11A1 and kidney cancer and identify novel, potentially effective therapeutics." (PMID 36182900, 2022). "All these observations confirmed that CYP11A1 overexpression induces G2/M phase arrest in kidney cancer cells by regulating cell cycle-related kinases." (PMID 36182900, 2022). "Therefore, we designed a screening model using a CYP11A1-overexpressing kidney cancer cell line to identify lead compounds for the treatment of kidney cancer." (PMID 38036976, 2023). "However, the molecular mechanisms of CYP11A1 and kidney cancer proliferation remain unclear." (PMID 36182900, 2022).
metastatic disease (2 papers, 2022 to 2024). "Of the many APUC genes that have been associated with the activation of AR, we found that 6 (HSD3B1, HSD3B2, CYP11A1, CYP11B1, CYP17A1, and CYP3A43) exhibit robust association in prostate and metastatic tumors and were mutually exclusive with heightened AR activity." (PMID 39207857, 2024). "Six APUC genes (HSD3B1, HSD3B2, CYP3A43, CYP11A1, CYP11B1, CYP17A1) exhibited coalescent gene behavior in a cohort of metastatic tumors (n = 208)." (PMID 39207857, 2024).
pancreatic cancer (2 papers, 2010 to 2023). "Mito is an FDA-approved chemotherapeutic agent for the treatment of bladder, gastric, and pancreatic cancer treatment, which activates the enzymatic activity of CYP11A1." (PMID 38036976, 2023).
peanut allergy (2 papers, 2020 to 2025). "Beyond oncology, elevated steroidogenesis has been implicated in other pathological conditions, such as peanut allergy, where CYP11A1 inhibition has been proposed as a potential therapeutic approach." (PMID 40454094, 2025). "Although these results implicate a role for CYP11A1 in the development of peanut allergy, a number of important questions arise." (PMID 32497050, 2020). "Confirmation in a larger cohort of patients is now needed to determine if levels of CYP11A1 mRNA in activated CD4+ T cells can serve as a predictor of peanut allergy." (PMID 32497050, 2020). "Even considering these caveats, the results identify a CYP11A1-IL-13 axis in the development of peanut allergy in children, supporting potential targeting of CYP11A1 as a novel treatment strategy in controlling peanut allergy." (PMID 32497050, 2020). "Beyond cancer, posaconazole’s CYP11A1 inhibition could be explored in other conditions characterized by elevated steroidogenesis, such as peanut allergy." (PMID 40454094, 2025).
psoriasis (2 papers, 2024 to 2025). An autoimmune condition characterized by red, well-delineated plaques with silvery scales that are usually on the extensor surfaces and scalp. "CYP11A1 expression is decreased in patients with AD and psoriasis and may play a role in the pathogenesis of inflammatory skin diseases." (PMID 39201319, 2024).
renal carcinoma (2 papers, 2022 to 2025). A carcinoma arising from the epithelium of the renal parenchyma or the renal pelvis. "Our results suggest that CYP11A1 overexpression recovered the disturbed cell cycle arrest distribution in renal carcinoma cell line Caki-1 through G2/M arrest and C-Raf/ERK/JNK pathway." (PMID 36182900, 2022). "Normal and renal carcinoma cell lines (HEK293 and Caki-1) were transfected with plasmid encoding CYP11A1 to overexpress the P450scc protein." (PMID 36182900, 2022).
aging (1 paper, 2021). A developmental process that is a deterioration and loss of function over time. "Therefore, active forms of vitamin D3 including its canonical (1,25(OH)2D3) and noncanonical (CYP11A1-intitated) D3 derivatives as well as L3 derivatives are promising agents for the prevention, attenuation, or treatment of premature skin aging." (PMID 34445803, 2021).
Alzheimer disease (1 paper, 2022). A progressive, neurodegenerative disease characterized by loss of function and death of nerve cells in several areas of the brain leading to loss of cognitive function such as memory and language. "We question whether this small amount of CYP11A1 can account for the levels of pregnenolone found in human brains range, which range from 5.7 ng/g to 127.44 ng/g tissue with variations seen between different brain regions and between nondemented and Alzheimer’s disease patients." (PMID 35688208, 2022).
anaphylaxis (1 paper, 2020). An acute hypersensitivity reaction that occurs from exposure to an allergen. "Activation of the steroidogenic enzyme CYP11A1 was shown to be necessary for the development of peanut-induced intestinal anaphylaxis and IL-13 production in allergic mice." (PMID 32497050, 2020).
androgen insensitivity syndrome (1 paper, 2019). Androgen insensitivity syndrome (AIS) is a disorder of sex development (DSD) characterized by the presence of female external genitalia, ambiguous genitalia or variable defects in virilization in a 46,XY individual with absent or partial responsiveness to age-appropriate levels of androgens. "We identified novel mutations in the androgen receptor DNA sequence as well as in the CYP11A1 gene in individuals with clinically diagnosed Complete Androgen Insensitivity Syndrome." (PMID 31671693, 2019).
Anxiety (1 paper, 2021). Intense feelings of nervousness, tension, or panic often arise in response to interpersonal stresses. "Compared with their control counterparts, the offspring of the CYP11A1-ovexpressing dams displayed more symptoms of anxiety and spent less time in social interactions and more time in self-grooming and rearing, all indicators of autism-like behavior." (PMID 35002603, 2021). "In this study, we found that abnormal CYP11A1 gene expression in pregnant rats could induce anxiety and autism-like behavior in their offspring through the regulation of microglial immune activation and dysregulation of GABAR expression in the neurons." (PMID 35002603, 2021). "In this study, we found that abnormal CYP11A1 gene expression in pregnant rats could induce anxiety and autism-related behaviors in their offspring through the regulation of microglial immune activation and the dysregulation of gamma-aminobutyric acid type A (GABAA) receptor (GABAR) expression." (PMID 35002603, 2021). "Taken together, these results suggest that abnormal CYP11A1 gene expression in pregnant rats could lead to microglial immune activation and dysregulated GABAA receptor expression in their offspring and thereby anxiety and autism-related behavior." (PMID 35002603, 2021).
asthma (1 paper, 2016). "Computed score-based analyses of multiple high-throughput datasets (RegulomeDB Database) suggest a putative regulatory role of some of the asthma-associated CYP11A1 SNPs." (PMID 26750596, 2016). "Seven out of eight polymorphisms covered by the asthma-associated tagging SNPs are located in potential regulatory regions of CYP11A1 (promoter: N=6, introns: N=1)." (PMID 26750596, 2016). "Given the importance of CYP11A1 in the regulation of experimental asthma in mice, we determine if a predisposition to asthma in humans is influenced by CYP11A1 single-nucleotide polymorphisms (SNPs)." (PMID 26750596, 2016). "We observed three CYP11A1 tagging SNPs that decreased the risk for asthma in a case–control population." (PMID 26750596, 2016). "Most of the CYP11A1 polymorphisms covered by the asthma-associated tagging SNPs were located in regulatory regions of CYP11A1, indicating a potential allele-specific function." (PMID 26750596, 2016). "To determine if these findings in mice are relevant to asthma, we investigated if CYP11A1 is involved in the susceptibility of asthma in childhood." (PMID 26750596, 2016). "Both CYP11A1 SNPs, rs4886595 and rs4432229, are significantly associated with asthma only in individuals carrying homozygous asthma-risk alleles of rs2107301 (VDR)." (PMID 26750596, 2016). "An epistasic effect between genetic variants in CYP11A1 and VDR is implicated in humans due to protective effects on the development of asthma." (PMID 26750596, 2016). "An interaction between asthma-associated SNPs in CYP11A1 and VDR supported the relevance of CYP11A1 and VDR predisposing to childhood asthma." (PMID 26750596, 2016). "In humans, the data supported an epistatic effect between CYP11A1 and VDR polymorphisms, diminishing the risk to develop childhood asthma." (PMID 26750596, 2016). "An epistatic effect between CYP11A1 and VDR polymorphisms may contribute to the predisposition to childhood asthma." (PMID 26750596, 2016). "Further understanding of the molecular mechanisms by which 1,25D3, CYP11A1 and VDR interact to regulate the plasticity and/or stable conversion of CD8+ T cells may provide new targets and novel therapeutic strategies in asthma." (PMID 26750596, 2016).
atherosclerosis (1 paper, 2023). A disease characterized by the build-up of fatty material and calcium deposition in the arterial wall resulting in partial or complete occlusion of the arterial lumen. "Several other TG-affected genes showed weaker associations with atherosclerosis-related outcomes (ABCG1, AC004791.2, CPA3, CYP11A1, SLC12A3) or rheumatoid arthritis (GATA2, SMPDL3A) but were no longer statistically significant after correction for multiple testing (PFDR > 0.05)." (PMID 36725846, 2023).
autism (1 paper, 2021). Persistent deficits in social interaction and communication and interaction as well as a markedly restricted repertoire of activity and interest as well as repetitive patterns of behavior. "Recent genetic association studies have shown that single nucleotide polymorphisms (SNPs) of CYP11A1 were related to the pathogenesis of autism." (PMID 35002603, 2021). "In this study, we investigated the association between high CYP11A1 levels in pregnant rats and autism-like behavior in their offspring." (PMID 35002603, 2021). "A recent report has linked PCOS in mothers to an increased incidence of autism in their children, suggesting that this could be due to the altered CYP11A1 levels in the women." (PMID 35002603, 2021). "In conclusion, we have shown that during pregnancy, the dysregulated CYP11A1 may closely linked to the etiology of autism in offspring, at least in some subtypes." (PMID 35002603, 2021). "First, genetic variations in CYP11A1 could be regulated by SNPs surrounding the regulatory region, as recent genetic association studies have identified an SNP related to the autism phenotype in Chinese children." (PMID 35002603, 2021). "Our study also indicated that testosterone alone cannot induce TNF-α expression in the microglia, indicating that other hormones may be responsible for the link between CYP11A1 expression and autism." (PMID 35002603, 2021). "Considering the recent reports of a close relationship between placental insufficiency and autism, our results from this study confirmed that altered CYP11A1 levels could affect both placental development in the mother and neurobehavior in her offspring." (PMID 35002603, 2021). "Third, a recent study found altered pregnenolone levels in children with autism, which is similar to the finding in this study that the levels of the hormone were changed in the circulation of the offspring from CYP11A1-overexpressing dams." (PMID 35002603, 2021). "This is the first study to demonstrate that CYP11A1 could play a key role in the regulation of GABAergic signaling and autism-like behavior." (PMID 35002603, 2021). "This study further provides potential insights into the mechanism through which CYP11A1 mediates autism-related neurobehavior and identifies key signaling targets for future intervention in the pathogenesis of autism related to abnormal hormone secretion during pregnancy." (PMID 35002603, 2021). "On the basis of these findings, we hypothesized that CYP11A1 overexpression in the pregnant mother may induce autism-like behavior in her offspring." (PMID 35002603, 2021). "Given that the AD-CYP11A1 infection in pregnant rats led to autism-like neurobehavior in their offspring, and the in vitro cell model showed that CYP11A1 treatment altered GABAA subunit expression, we next investigated whether GABAA subunit expression was altered in vivo." (PMID 35002603, 2021).